CKS1B (CDC28 protein kinase regulatory subunit 1B)
Description:
Binds to the catalytic subunit of the cyclin dependent kinases and is essential for their biological function.
Synonyms: CKS1; PNAS-16; ckshs1; PNAS-18
Tractability: Small molecule: a structure with a bound ligand is known; a high-quality ligand is known. PROTAC: ubiquitination databases record sites on it; a small molecule that binds it is known.
Target class: Kinase; Protein kinase regulatory subunit; Enzyme
Gene: Protein-coding gene on chromosome 1 (154,974,641 to 154,979,251, forward strand). Ensembl gene ENSG00000173207.
Subcellular location (Human Protein Atlas): Cytosol; Mitochondria; Nucleoplasm; Vesicles
Pathways (Reactome):
Cell Cycle: Cyclin D associated events in G1; SCF(Skp2)-mediated degradation of p27/p21
Gene Ontology:
Molecular function: protein binding; cyclin-dependent protein serine/threonine kinase activator activity; histone binding; protein kinase binding; ubiquitin binding; cyclin-dependent protein serine/threonine kinase regulator activity
Biological process: regulation of mitotic cell cycle
Cellular component: cyclin-dependent protein kinase holoenzyme complex; nucleoplasm; SCF ubiquitin ligase complex
Genetic constraint (gnomAD): Loss-of-function variants: 5 observed, 10.61 expected, observed/expected ratio (o/e) 0.47, 90% interval 0.25 to 0.99. The upper end of that interval is the gene's LOEUF score, 0.99, which puts it in group 4 of 6, group 1 being the genes least tolerant of losing a copy. Missense variants: 41 observed, 82.54 expected, observed/expected ratio (o/e) 0.5, 90% interval 0.39 to 0.64. Synonymous variants: 20 observed, 26.88 expected, observed/expected ratio (o/e) 0.74, 90% interval 0.52 to 1.08.
Homologues: Orthologues: chimpanzee CKS1B (100% identical), dog CKS1B (100% identical), macaque CKS1B (100% identical), mouse Cks1b (100% identical), pig CKS1B (100% identical), rabbit CKS1B (100% identical), guinea pig CKS1B (99% identical), rat AABR07049223.1 (99% identical), mouse Cks1brt (94% identical), zebrafish cks1b (87% identical), tropical clawed frog CKS1B (81% identical), Drosophila melanogaster Cks85A (66% identical), and 1 more. Paralogues in human: CKS2 (81% identical), NIP7 (33% identical).
Diseases named in the same sentence as CKS1B in open-access papers:
CKS1B is named in the same sentence as 74 diseases in open-access papers, as found by Europe PMC text mining. Sharing a sentence is not in itself a finding about the gene and the disease. The quoted sentences say what the papers report.
multiple myeloma (30 papers, 2010 to 2024). "CKS1B amplification and overexpression have been reported in breast cancer and multiple myeloma and has been associated with poor prognosis in both." (PMID 38523186, 2024). "Consistent with these previous observations, we observed copy gain and up-regulation of CKS1B, which is a cell cycle regulator that has been linked to and promotes cisplatin and other drug resistance in myeloma, breast cancer, and non-small cell lung cancer." (PMID 26755726, 2016). "CKS1B is one of the 70 high-risk signature genes associated with poor outcome in newly diagnosed myeloma." (PMID 20930946, 2010). "In particular, they found that overexpression of CKS1B, a cell cycle regulator, was highly associated with an aggressive clinical course and was found to promote myeloma cell growth by activating cyclin-dependent kinases and through SKP2-mediated ubiquitination of the tumor suppressor p27Kip1 34,36." (PMID 33927196, 2021). "In hematologic malignancies, gain of 1q has been associated with overexpression of the CKS1B gene in 1q21 in multiple myeloma and with upregulation of B4GALT3 (1q23), DAP3 (1q22), RGS16 (1q25), TMEM183A (1q32), and UCK2 (1q24) in a few dup(1q)-positive HeH cases." (PMID 29626196, 2018). "Moreover, individual components of the SCF complex, including Cullin1, S-phase kinase associated protein 2 (Skp2), copper metabolism domain containing 1 (Commd1), and cyclin-dependent kinases regulatory subunit 1(Cks1b) have been linked to Bortezomib resistance in multiple myeloma." (PMID 30885218, 2019). "In fact, CKS1B was the only previously suggested myeloma driver on 1q21 that was significantly upregulated in our analysis." (PMID 38493239, 2024). "Subsequently, CKS1B was later shown to activate myeloma cell growth through upregulation of the STAT3 and MEK/ERK pathways." (PMID 33927196, 2021). "Another study showed elevated CKS1B promoted myeloma cell drug resistance by activation of STAT3 signaling." (PMID 32960462, 2021). "It has been reported in breast cancer, lung cancer, ovarian carcinoma, and multiple myeloma that the overexpressed CKS1B resulted in the tumor progression by promoting the degradation of p27Kip1 and patients with high CKS1B expression presented poor prognosis." (PMID 34925510, 2021). "In the human myeloma cell lines (JJN3, OCI-MY5, and XG1), overexpressing CKS1B, silencing of CKS1B expression was associated with the upregulation of p27KIP1 which resulted in inhibition of the cell growth." (PMID 33445467, 2021). "Enhanced expression of CKS1B in a number of cancers such as myeloma, breast cancer, lymphoma, renal carcinoma, ovarian cancer, salivary, and oesophageal cancers etc. has been associated with poor prognosis." (PMID 30937183, 2019). "CKS1B has been shown overexpression in aggressive disease and regulated multiple myeloma growth and survival through SKP2- and p27Kip1-dependent and -independent mechanisms." (PMID 27270326, 2016). "CKS1B is overexpressed in many malignancies including breast, prostate, cervical cancers, nasopharyngeal carcinoma, and multiple myeloma, where it promotes cell proliferation (44, –, 49)." (PMID 25477524, 2015). "In multiple myeloma (MM), an aggressive bone marrow cancer originating from terminally differentiated B cells, CKS1B is frequently overexpressed." (PMID 22624029, 2012). "Nifuroxazide treatment decreased p-STAT3 in both EV- and CKS1B-transfected myeloma cells compared with untreated controls by western blot, and it did not alter the total protein and phosphorylation of MEK/ERK1 (data not shown), confirming its specificity." (PMID 20930946, 2010). "The aim of the present study was to further clarify the functional role of CKS1B in myeloma cell survival and drug-resistance by investigating CKS1B-induced SKP2- and p27Kip1-independent signaling pathways." (PMID 20930946, 2010). "The effects of IGF-1 treatment on CKS1B-shRNA-induced myeloma cell death and growth inhibition were evaluated." (PMID 20930946, 2010).
multiple myeloma (continued). "Here we demonstrate the crucial role of CKS1B in multiple myeloma (MM) progression and define CKS1B-mediated SKP2/p27Kip1-independent down-stream signaling pathways." (PMID 20930946, 2010). "Our results show that forced-expression of CKS1B in MM cells induces multidrug-resistance, providing direct evidence for the crucial role of CKS1B in myeloma progression." (PMID 20930946, 2010). "The effects of BCL2-transfection on CKS1B-shRNA induced myeloma cell growth inhibition and death were evaluated." (PMID 20930946, 2010). "In conclusion, this study further demonstrates that CKS1B plays a crucial role in MM cell growth and survival and for the first time provides direct evidence for the crucial role of CKS1B in myeloma multidrug-resistance." (PMID 20930946, 2010). "RNA interference of CKS1B mRNA in myeloma cells led to reduced CKS1B mRNA and protein, an accumulation of p27Kip1, and profound growth inhibition." (PMID 20930946, 2010). "We identified STAT3 and MEK/ERK/BCL2 as CKS1B-downstream signaling pathways; and thereby provided targets for the development of new therapeutic approaches for CKS1B over-expressing myeloma and other tumor malignancies." (PMID 20930946, 2010). "Western-blots detected increased p-STAT3 in these CKS1B-silenced myeloma cells compared with untreated, SCR- or CKS1B-shRNA-transfected controls, confirming activation of STAT3 in IGF-1-treated cells." (PMID 20930946, 2010). "We previously showed that CKS1B is essential for myeloma cell growth and survival by using gene knockdown." (PMID 20930946, 2010). "Our findings explain why SKP2 knockdown or p27Kip1 over-expression induces less myeloma cell growth inhibition and cell death than CKS1B knockdown." (PMID 20930946, 2010). "Another study highlighted that the drug resistance of myeloma cells may be induced through the stimulation of the STAT3 signaling by CKS1B." (PMID 36405738, 2022). "A study has shown that CKS1B overexpression promoted drug resistance in myeloma." (PMID 34568067, 2021). "Firstly, significant upregulation of CKS1B protein and mRNA level in OS was demonstrated, which is consistent with the findings of highly expressed CKS1B in nasopharyngeal, breast cancer, non-small-cell lung cancer, Burkitt lymphoma, and multiple myeloma." (PMID 34925510, 2021). "MEK/ERK pathway is activated in aggressive CKS1B-overexpressing plasma cell myeloma cells." (PMID 24608798, 2014). "Since the STAT3 and MEK/ERK signaling pathways were both involved in CKS1B-induced myeloma cell growth and survival, a combined targeting of these signaling pathways might induce synergistic cytotoxicity in myeloma cells." (PMID 20930946, 2010). "U0126 decreased p-MEK1/2 and p-ERK1/2 in both EV- and CKS1B-transfected myeloma cells." (PMID 20930946, 2010). "Thus, it is reasonable to conclude that CKS1B mediates myeloma cell growth and drug-resistance through activation of STAT3 and MEK/ERK/BCL2 signaling pathways." (PMID 20930946, 2010). "In addition, CKS1B is considered a predictor of adverse survival in patients with multiple myeloma." (PMID 36405738, 2022). "Increased expression of CKS1B is a progression event, but it is possible that CKS1B may be heterogeneously expressed in myeloma cells at diagnosis, and current treatments ineffectively eliminate the small populations of CKS1B high-expression myeloma cells, leading to relapse." (PMID 20930946, 2010). "Myeloma cells with forced CKS1B expression are more sensitive to treatment with specific inhibitors targeting these signaling pathways, while stimulation of these signaling pathways partially abrogates myeloma cell death and growth inhibition, induced by CKS1B knockdown." (PMID 20930946, 2010).
multiple myeloma (continued). "CKS1B was previously reported to promote drug resistance in myeloma cells through activation of the JAK/STAT3 signaling pathway, which revealed a link between CKS1B and JAK/STAT3 pathway." (PMID 34408811, 2021). "Recent studies found CKS1B could regulate STAT3 and further influence cancer development of lung cancer and myeloma." (PMID 32960462, 2021). "Additionally, CKS1B represents an oncogene that has been reported increased in retinoblastoma, HCC, nasopharyngeal carcinoma and multiple myeloma." (PMID 32183400, 2020). "Expression of CKS1B, which maps to a previously defined amplicon at 1q21 and regulates SCFSkp2-mediated ubiquitination and proteolysis of the CDK inhibitor p27Kip1, was significantly overexpressed in newly diagnosed myeloma patients with a short survival." (PMID 20930946, 2010). "Thus, our findings clarify the SKP2/ p27Kip1-independent mechanisms of CKS1B activity in maintaining myeloma cell growth and survival, and also provide a rationale for specifically targeting STAT3 and MEK/ERK/BCL2 in aggressive CKS1B-overexpressing MM." (PMID 20930946, 2010). "Although BCL2-cDNA and CKS1B-shRNA doubly-transfected cells clearly showed cell growth inhibition and death compared with SCR-transfected control cells (p <0 .05), BCL2 transfection partially abrogated myeloma cell growth inhibition and death induced by CKS1B-silencing (p < 0.05)." (PMID 20930946, 2010). "A predictive model developed by Mohamad and others, based on five genes including CKS1B, CCT2, PRKDC, NONO, and UBE2A, successfully predicted the prognosis of patients with multiple myeloma and has been validated in several independent datasets." (PMID 39046884, 2024). "However, CKS1B, coding for the CDC28 protein kinase regulatory subunit 1B and known to be overexpressed in multiple myeloma, was clearly not overexpressed." (PMID 29626196, 2018). "Since inhibitors of MEK/ERK signaling pathway may induce some non-specific effects on myeloma cell growth and survival, we constitutively activated the MEK/ ERK signaling pathway by lentivirus-vector-mediated MEK1-cDNA transfection in CKS1B-silenced KMS28PE, OCI-MY5 and XG1 cells." (PMID 20930946, 2010).
breast carcinoma (13 papers, 2010 to 2024). "To evaluate the potential association of NQO1 and CKS1B expression with patient outcomes, we performed a Kaplan-Meier survival analysis using both TCGA colorectal and breast cancer datasets, which revealed a strong correlation of high NQO1 and CKS1B expression with poor prognosis." (PMID 36793872, 2023). "Because increased copy number and expression of CKS1B has been linked to cisplatin resistance, we hypothesized that the anti-miR induction would promote resistance to cisplatin in breast cancer cells." (PMID 26755726, 2016). "Another study suggested that the drug-resistant oncogene CKS1B is responsible for the resistance of breast cancer cells to the cisplatin treatment." (PMID 30577536, 2018). "Breast cancer cells over-expressed CKS1B by regulating the miR-23a-induced suppression of the histone demethylase KDM4A." (PMID 30577536, 2018). "Consistent with increased CKS1B expression, miRNA inhibition reduced breast cancer cell sensitivity to cisplatin." (PMID 26755726, 2016). "These tumors exhibited amplification and overexpression of the drug resistance gene CKS1B, which we recapitulated in hypoxic breast cancer cells." (PMID 25995187, 2015). "We further demonstrated in breast cancer cells that CKS1B exhibited site-specific copy gain and had increased expression upon hypoxic exposure." (PMID 25995187, 2015). "Most importantly, we demonstrated that hypoxic tumors predicted amplification and expression for the drug-resistant oncogene CKS1B, which was confirmed in a human breast cancer cell line treated with hypoxia." (PMID 25995187, 2015). "There are many candidate genes; CENF, KIF14, DTL, NEK2, CKS1B, ASPM and EXO1 each of which are significantly associated with poor clinical outcome in breast cancer patients." (PMID 25312014, 2014). "The subsequent filtering with the combined p-value <0.005 across 6 datasets, yielded 7 candidate genes ASPM, KIF14, NEK2, DTL, CENPF, CKS1B and EXO1 that are significantly associated with poor clinical outcome of the breast cancer patients." (PMID 24147022, 2013). "Our results are consistent with the recent investigations which showed that CKS1B stimulated MEK/ERK signaling pathway in the breast cancer cells." (PMID 20930946, 2010). "Consistent with previous reports 3,40, we found that expression levels of NQO1 and CKS1B reported in TCGA colorectal and breast cancer datasets were higher in colorectal and breast cancer compared with normal tissues and that CKS1B expression was dependent on the level of NQO1 expression." (PMID 36793872, 2023). "CKS1B binds to the catalytic subunit of cyclin-dependent kinases and is involved in the control of their biological functions, and inhibition of CKS1B expression blocks breast cancer cell entry into the M phase of the cell cycle." (PMID 34650929, 2021). "Besides, in colon cancer and breast cancer, CKS1B was found to be negatively correlated with prognosis." (PMID 34845438, 2021). "Besides, transcripts ENST00000524816.7 and ENST00000471245.1 were respectively noncoding regions of gene TRIM29 and CKS1B, which were responsible for breast cancer proliferation, metastasis and invasion." (PMID 34094912, 2021). "Previously, we demonstrated that breast tumors and breast cancer cells were able to generate copy gain and increased expression of the drug-resistant oncogene CKS1B (located at 1q21.3 inside the amplified region of tumors with hsa-mir-23a loss) upon hypoxic exposure." (PMID 26755726, 2016). "Commonality with most of the short-listed genes (CENPF, KIF14, NEK2, CKS1B and ASPM) is their positive association with proliferation marker Ki-67, thereby, indicating their possible role in cell cycle related dysregulations and the resultant proliferation of breast cancer cells." (PMID 24147022, 2013). "In breast cancer, NQO1 expression is highly increased, and expression of CKS1B is also increased, albeit to a slightly lesser degree, but in both cases this increase is dependent on tumor stage." (PMID 36793872, 2023).
breast carcinoma (continued). "Further assessment of TCGA colorectal cancer and breast cancer databases supported correlations of high NQO1 and CKS1B expression with tumor stage." (PMID 36793872, 2023). "While the breast cancer candidacy of CENPF, KIF14, NEK2, DTL, CKS1B, ASPM and EXO1 genes have been identified earlier, there is only one prominent report indicating the candidacy of EXO1 in breast cancers and remains to be investigated." (PMID 24147022, 2013). "Using the breast cancer line MDA-MB-231, we observed copy gain for CKS1B upon hypoxic exposure, which was reversed upon return to normoxia." (PMID 25995187, 2015).